PIANP (PILR alpha associated neural protein)
Description:
Acts as a ligand for PILRA in neural tissues, where it may be involved in immune regulation.
Synonyms: C12orf53; PANP; DKFZp547D2210; LEDA1; leda-1
Tractability: Antibody: its Gene Ontology location is reachable by antibodies, with high confidence; UniProt predicts a signal peptide or a membrane-spanning region. PROTAC: its protein half-life has been measured.
Gene: Protein-coding gene on chromosome 12 (6,693,791 to 6,700,848, reverse strand). Ensembl gene ENSG00000139200.
Subcellular location: Membrane
Subcellular location (Human Protein Atlas): Nucleoplasm
Pathways (Reactome):
Immune System: Immunoregulatory interactions between a Lymphoid and a non-Lymphoid cell
Gene Ontology:
Molecular function: protein binding
Biological process: regulation of immune response
Cellular component: basolateral plasma membrane; membrane; plasma membrane
Genetic constraint (gnomAD): Loss-of-function variants: 14 observed, 21.35 expected, observed/expected ratio (o/e) 0.66, 90% interval 0.43 to 1.02. The upper end of that interval is the gene's LOEUF score, 1.02, which puts it in group 4 of 6, group 1 being the genes least tolerant of losing a copy. Missense variants: 322 observed, 325.45 expected, observed/expected ratio (o/e) 0.99, 90% interval 0.9 to 1.09. Synonymous variants: 149 observed, 136.06 expected, observed/expected ratio (o/e) 1.1, 90% interval 0.96 to 1.25.
Homologues: Orthologues: chimpanzee PIANP (100% identical), macaque PIANP (100% identical), pig PIANP (99% identical), rabbit PIANP (99% identical), dog PIANP (98% identical), rat Pianp (95% identical), guinea pig PIANP (94% identical), mouse Pianp (93% identical), tropical clawed frog pianp (37% identical).
Diseases named in the same sentence as PIANP in open-access papers:
PIANP is named in the same sentence as 8 diseases in open-access papers, as found by Europe PMC text mining. Sharing a sentence is not in itself a finding about the gene and the disease. The quoted sentences say what the papers report.
developmental delay (2 papers, 2020 to 2025). "A case study described a boy with a homozygous nonsense variant in PIANP, who presented with global developmental delay." (PMID 40756990, 2025). "A recent case description of a boy with global developmental delay and homozygous nonsense variant in PIANP supports the hypothesis that PIANP is involved in the control of behavioral traits in mammals." (PMID 31511635, 2020).
PIANP also shares sentences with these, for which no sentence is quoted: cancer (1 paper); Epileptic encephalopathy (1); Intellectual disability (1); neurodevelopmental disorder (1); postherpetic neuralgia (1); Rett-like syndrome (1); tumor (1).